MYC (MYC proto-oncogene, bHLH transcription factor)
Diseases named in the same sentence as MYC in open-access papers (continued):
Sharing a sentence is not in itself a finding about the gene and the disease.
B-cell lymphoma (continued). "Patients with B cell lymphomas bearing MYC translocation combined with translocation involving other genes, such as BCL2, BCL3, or BCL6, defined as double-hit lymphoma (DHL), have a poor prognosis." (PMID 28595585, 2017). "MINCR is up-regulated by MYC in both model cell lines and in all B-cell lymphomas carrying a MYC-translocation resulting in MYC overexpression." (PMID 28704924, 2017). "In this review, we discuss the role that c-MYC plays in the pathogenesis of B-cell lymphomas, the molecular alterations that lead to c-MYC dysregulation, and their effect on prognosis and diagnosis in specific types of B-cell lymphoma." (PMID 28379189, 2017). "c-MYC has been shown to cooperate with transcriptionally activated cyclin D1 in oncogenic transformation of B-cell lymphomas in transgenic mice." (PMID 28379189, 2017). "Enforced expression of the mir-17–92 cluster acted with c-MYC expression to accelerate tumor development in a mouse B-cell lymphoma model." (PMID 28696359, 2017). "This review will summarize the roles of MYC in B cell development and oncogenesis, as well as its significance for current B cell lymphoma classification." (PMID 28375188, 2017). "The purpose of this study is to evaluate the effectiveness of Myc-IHC in predicting MYC rearrangement by FISH (the current gold standard) in mature B-cell lymphomas." (PMID 28983465, 2017). "Knockout of DNMT3B accelerates the initiation of MYC-driven T- and B-cell lymphoma in mouse models (EμSRα-tTA;tet-o-MYC and Eμ-MYC), while increased DNA methylation of DNMT3B targets delays leukemogenesis." (PMID 29100357, 2017). "This cluster facilitates formation of B-cell lymphomas in E(mu)-c-MYC transgenic mice, and its overexpression is involved in the formation of malignant B-cell lymphomas." (PMID 28696359, 2017). "The effect of dinaciclib on MYC level through inhibition of CDK9 in MYC-driven tumor cells was reported previously in a study of B cell lymphoma cell lines." (PMID 27486754, 2016). "In lymphomas arising in the Eμ-Myc transgenic mouse, a model of human B cell lymphomas with MYC involvement, expression of TTP provokes growth arrest." (PMID 27825143, 2016). "The designation double-hit lymphoma (DHL) has been used for a B-cell lymphoma carrying a MYC/8q24 rearrangement in combination with a rearrangement involving either BCL2, BCL6, or rarely other known oncogenes." (PMID 26573234, 2016). "Double-hit lymphomas (DHLs) are a heterogeneous group of mature B-cell lymphomas that harbor rearrangements of MYC and BCL2." (PMID 27606052, 2016). "Some contexts were known to have active MYC function (e.g. B cell lymphoma), whereas others were new contexts in which MYC's function was unestablished at the time the 51 core target genes were originally reported." (PMID 26350211, 2016). "In another study, Oki et al21 analyzed the outcome of 129 cases of DHL at MD Anderson; DHL was defined as B-cell lymphoma with translocations and/or extra signals involving MYC plus BCL2 and/or BCL6." (PMID 27115017, 2016). "In the literature B-cell lymphomas with concurrent MYC/BCL2 or MYC/BCL6 rearrangements are grouped together as double-hit B-cell lymphomas." (PMID 26573234, 2016). "We employed SILAC-based quantitative proteomics to identify miR-17-19b targets upon a mild overexpression of the cluster in B cell lymphomas, established from λ-MYC transgenic mice." (PMID 26977435, 2016). "miR-124 can suppress the fitness of B-cell lymphomas by targeting MYC and BCL2, which are coexpressed in B-cell lymphomas and associated with the poor prognosis." (PMID 27757114, 2016). "There were 49 patients with MYC/BCL2 DHL who had a history of FL (n = 46) or other type of low-grade non-Hodgkin B cell lymphoma (n = 3)." (PMID 27203548, 2016). "In human GC-derived B cell lymphomas, the MYC gene is frequently involved in chromosomal translocations." (PMID 26416427, 2015).
B-cell lymphoma (continued). "The term ‘DH lymphoma’ was initially used to describe mature-B-cell lymphomas with a chromosomal breakpoint affecting the MYC locus in combination with another recurrent breakpoint, such as BCL2, BCL6, BCL3 or CCND1." (PMID 26517511, 2015). "Prdm11, a tumour suppressor gene in MYC-driven B cell lymphomas and involved in transcriptional regulation, was recently associated with pulmonary function in humans in a genome-wide association study (GWAS)." (PMID 26263558, 2015). "In fact, while the majority of B cell lymphomas derived from the Eμ-MYC transgene have a mature B-cell phenotype, B-cell lymphomas resulting from the collaboration between miR-17-19b and MYC are mostly derived from precursor cells." (PMID 26305986, 2015). "The promoter region of both miR-29 clusters contains a putative E-box Myc binding site and increased expression of c-MYC, such as in B-cell lymphoma, contributes to suppress miR-29s expression." (PMID 25968566, 2015). "Using rabbit monoclonal antibody (Epitomics, clone Y69) that targets the N-terminus of MYC to assess the differential expression of MYC in various aggressive B-cell lymphomas." (PMID 26416427, 2015). "MYC translocation, a biological hallmark of Burkitt lymphoma, can also be detected in DLBCL and B cell lymphoma unclassifiable with features intermediate between DLBCL and Burkitt lymphoma." (PMID 26158410, 2015). "There are several regulatory factors and dysregulated signaling that lead to MYC up-regulation in B-cell lymphomas." (PMID 26416427, 2015). "MYC rearrangement has been observed in 5-10% of diffuse large B-cell lymphomas and up to 50% of high-grade B-cell lymphomas other than Burkitt lymphoma." (PMID 26416427, 2015). "Recent studies have highlighted the importance of assessing MYC rearrangement in aggressive B-cell lymphomas, mainly DLBCL, as well as the detection of protein expression." (PMID 26158410, 2015). "We profiled the expression levels of both MYC and the mature forms of miR-17-19b members in human Burkitt lymphoma (BL) cell lines and in MYC-transformed pre-tumoral and mature B cell lymphomas isolated from λ-MYC transgenic mice." (PMID 26555894, 2015). "Over-expression of either MYC or N-MYC under the control of the B cell-specific Eμ enhancer results in development of pro-B cell lymphomas." (PMID 26453442, 2015). "MYC rearrangements, like other high-grade B-cell lymphomas of aggressive type, are found in near 50% and frequently correlated with EBV infection and worse prognosis." (PMID 25408850, 2014). "In this study, we aimed at identifying c-MYC-reactive T-cells to target a poorly immunogenic c-MYC-overexpressing B-cell lymphoma." (PMID 24130880, 2013). "In aggressive B cell lymphoma, miR-29a is repressed by MYC within a co-repressor complex that also includes HDAC3 and EZH2." (PMID 24348513, 2013). "The proto-oncogene c-MYC plays a crucial role in the pathogenesis of a large number of human tumors including B-cell lymphomas and leukemias as well as a variety of different epithelial tumors." (PMID 24130880, 2013). "Another possible explanation is that the death receptor pathway and its regulation by FLIPL is important for certain MYC-induced tumors, such as Eμ-myc driven B cell lymphoma, but less important in the case of AML." (PMID 22393362, 2012). "To confirm that c-MYC regulation extended to the entire miR-23a cluster, we used the c-MYC-over-expressing cell line P-493B, a human B-cell lymphoma line engineered with a tet-off system." (PMID 23236401, 2012). "In another transplantation model, overexpression of MYC resulted in development of aggressive pre-B cell lymphomas, with low penetrance and after long latency (>100 days)." (PMID 22393362, 2012).
B-cell lymphoma (continued). "The transcription factor and cell cycle regulator MYC (c-MYC) is a well-recognized oncoprotein in B-cell lymphoma." (PMID 22511926, 2012). "In the left hand side color bars of the heatmaps we have marked the direction of MYC regulation in MCF7 cells (Musgrove_Myc_U+D) as well as the direct targets of MYC defined in B cell lymphoma (Zeller_Myc_B)." (PMID 19270750, 2009). "However, MYC-driven B cell lymphomas, particularly HGBCL with MYC and BCL2 rearrangements, frequently silence surface BCR/CD79B expression, limiting the therapeutic reach of CD79B-directed ADCs and underscoring the need for complementary treatment strategies." (PMID 41668618, 2026). "Primary thyroid high-grade B-cell lymphoma with MYC rearrangements can be observed in HT." (PMID 40364944, 2025). "Similarly to aggressive B-cell lymphomas, this group of tumors has a complex genomic landscape with numerous copy number anomalies, and rearrangements of MYC and BCL2 are detected in 11–21% and 9–29% of cases, respectively." (PMID 41008822, 2025). "Subclassification into these entities is important to evaluate prognosis and treatment options, as some subtypes, such as diffuse large B-cell lymphoma/high-grade B-cell lymphoma with MYC and BCL2 rearrangements (DLBCL/HGBL-MYC/BCL2), have worse prognosis and require alternative treatment regimens." (PMID 39790106, 2025). "Burkitt lymphoma (BL) is a rare, highly aggressive, MYC-driven B-cell non-Hodgkin lymphoma (NHL)." (PMID 40703543, 2025). "The pathological diagnosis: Based on BCL-2 expression being completely negative, together with the germinal center phenotype, very high Ki-67, and the presence of MYC rearrangement, the pathological diagnosis was aggressive B-cell lymphoma of the cervix, consistent with Burkitt’s lymphoma." (PMID 41561748, 2025). "Similarly, earlier studies reported that NAC and vitamin C can reduce tumor growth in subcutaneous MYC-driven B-cell lymphoma." (PMID 40646353, 2025). "Recurrent gene fusions and chromosomal rearrangements involving MYC, BCL2, and BCL6 are hallmark genetic events in DLBCL and are defining features of specific DLBCL subtypes and high-grade B-cell lymphomas (HGBCL), as per the World Health Organization (WHO) 2016 and 2022 classifications." (PMID 41010038, 2025). "This had been used to argue for the classification of rare cases of TdT‐positive blastoid B‐cell lymphoma with both MYC and BCL2 translocations as B‐LBL in the revised fourth edition of the World Health Organization classification of haematolymphoid tumours (WHO‐HAEM4R)." (PMID 41047873, 2025). "The term high-grade B-cell lymphoma with dual rearrangements of MYC and BCL2 and/or BCL6 from the previous edition of WHO has been conceptually reframed and reassigned to diffuse large B-cell lymphoma/high-grade B-cell lymphoma with MYC and BCL2 rearrangements (DLBCL/HGBL-MYC/BCL2)." (PMID 39038016, 2024). "As many as 19% of patients had high-grade B-cell lymphoma with MYC and BCL2 or BCL6-Rearrangement." (PMID 38893108, 2024). "FNAB with cell block is an equally effective alternative to core biopsy and excisional biopsy for assessment of MYC, BCL2, and BCL6 FISH, which is required for identification of the clinically aggressive subset of large B-cell lymphomas that carry both MYC and BCL2 rearrangements." (PMID 38903717, 2024). "B-cell lymphomas with MYC, BCL2, BCL6, and CCND1 rearrangements are rare entities." (PMID 38914869, 2024). "One variable that had not been previously considered is whether the morphological changes associated with apoptotic cell death influences the incidence, characteristics or severity of c-MYC-induced B cell lymphomas." (PMID 38616733, 2024). "In addition, important adaptations have also been made in the previous category of high-grade B-cell lymphomas with dual rearrangements of MYC and BCL2 and/or BCL6 of the WHO-HAEM4R." (PMID 38835969, 2024).
B-cell lymphoma (continued). "Pathologic review of the biopsy material revealed two unusual cases of MYC-R B-cell lymphoma: a case of a 6-year-old boy with BL-like morphology, isolated MYC::IGH rearrangement, CD10 positivity and a high Ki67 proliferative index (> 95%) showed TdT positivity." (PMID 38561469, 2024). "B-cell lymphomas require higher MYC levels to maintain their rapid proliferation rate." (PMID 36900005, 2023). "MINCR is upregulated by MYC in MYC-positive B-cell lymphomas." (PMID 37215074, 2023). "Importantly, 5%-15% of large B-cell lymphomas bear a translocation in MYC and BCL2 or BCL6, and 20%-30% of the cases are double expressors." (PMID 37457123, 2023). "It is defined as an aggressive B-cell lymphoma harboring a characteristic 11q gain/loss pattern without MYC rearrangement." (PMID 37190213, 2023). "MYC, a master regulator of multiple cellular processes such as cell proliferation, apoptosis and differentiation, is one of the most commonly rearranged oncogenes in B-cell lymphoma." (PMID 37958379, 2023). "In pediatric patients, large/high-grade B-cell lymphoma with 11q aberration is less frequent than MYC breakpoint-positive Burkitt lymphoma, occurs at older age, shows less male predominance, lower LDH, less abdominal involvement and it is characterized by an excellent prognosis." (PMID 36460764, 2023). "Our analysis reveals that Tom+ (AID-experienced) cells make only a minor contribution to tumors in these mice and that B cell lymphomas generated in the λ-MYC model originate from B cells at various maturation stages, with only a small fraction of them resembling BL." (PMID 37809061, 2023). "This concept led us to test whether exacerbating the disruption of redox homeostasis caused by IACS‐010759 could reinforce its anticancer activity against MYC‐driven B‐cell lymphomas." (PMID 37158102, 2023). "To evaluate the 5-Aza-‘2 and TAK981 combination treatment in B cell lymphoma, we set up a panel of ten different B cell lymphoma cell lines, including Burkitt lymphomas which are classically MYC-driven tumors and therefore of interest for treatment with TAK981." (PMID 36792656, 2023). "Deregulated expression of the oncogenic transcription factor MYC in B‐cell lymphoma induces a vulnerability to disruption of redox homeostasis by pharmacological treatment with the electron transport chain (ETC) complex I inhibitor IACS‐010759 and high‐dose ascorbate." (PMID 37158102, 2023). "In line with this hypothesis, researchers recently found that genetic or pharmacological inhibition of sumoylation diminishes the survival of MYC-positive B-cell lymphoma cells in culture, while also impairing disease maintenance in mouse xenograft models." (PMID 35269436, 2022). "However, MYC translocations also occur in around 15% of DLBCL, and elevated expression of MYC correlates with poor clinical prognosis in B-cell lymphoma." (PMID 36068335, 2022). "However, non-canonical E-box (CACATG) and E-box-independent mechanisms contribute to the binding of MYC to roughly 5000 promoter sites in B-cell lymphoma." (PMID 36611833, 2022). "c-MYC is an established essential regulator for B-cell lymphoma cell growth." (PMID 36167829, 2022). "Differently from previous studies that have shown IBTK as a potential transcriptional target of MYC in MYC-driven B-cell lymphomas, in this study, we raised the hypothesis of an upstream effect exerted by IBtkα in regulating the expression of MYC gene." (PMID 35216159, 2022). "High-grade B-cell lymphoma (HGBL) with MYC and Bcl-2 and/or Bcl-6 rearrangements is an aggressive mature B-cell lymphoma that harbours a MYC rearrangement at chromosome 8q24 and a rearrangement in Bcl-2 (at chromosome 18q21) and/or in Bcl-6(at chromosome 3q27)." (PMID 36618391, 2022). "Dysregulation of MYC is essential in the pathogenesis of a number of B-cell lymphomas." (PMID 34417556, 2022).
B-cell lymphoma (continued). "Studying the chromatin organization beyond the levels of nucleosomes might further explain the origin of the characteristic MYC translocations found in human B-cell lymphoma." (PMID 36611833, 2022). "MXD1 is a transcription factor that belongs to the MYC/MXD/MAX family, and is implicated in the pathophysiology of avian influenza virus infections, intracerebral hemorrhage, and various cancers such as osteosarcoma, lung adenocarcinoma and B cell lymphoma." (PMID 35609226, 2022). "We used PLA to uncover a close cellular localization of DNAJA3 with MYC in B-cell lymphoma cells." (PMID 36068335, 2022). "M-100 induces massive apoptosis in human and murine MYC-overexpressing B-cell lymphoma cells." (PMID 36068335, 2022). "Indeed, we and others showed that tigecycline was synthetic‐lethal with MYC overexpression in cultured B‐cells, and killed MYC‐driven B‐cell lymphomas." (PMID 36214609, 2022). "Indeed, the synergy between c-MYC and miR-17-19b, a truncated version of the miR-17-92 cluster, relevantly contributes to B cell lymphoma initiation as well as to lymphoma cell homeostasis." (PMID 35883486, 2022). "However, alterations in the MYC gene and expression of the MYC protein have been identified in aggressive B-cell lymphomas other than BL, such as DLBCL, plasmablastic lymphoma, and ALK-positive large B-cell lymphoma." (PMID 35328266, 2022). "Besides diffuse large B-cell lymphoma and Burkitt lymphoma, MYC expression has been linked to Richter’s syndrome, which is the transformation of CLL into a more aggressive B-cell lymphoma." (PMID 34417556, 2022). "Moreover, the loss of DYNLL1 dramatically delays the development and expansion of MYC-driven B-cell lymphoma in mice due to increased BIM-mediated apoptotic cell death, although BIM levels are not elevated." (PMID 35619131, 2022). "PLK1 is also considered as an oncotarget for aggressive B‐cell lymphomas since it stabilizes MYC." (PMID 34605140, 2021). "Although an isolated MYC translocation is a hallmark of BL, this finding can also be found in other aggressive B‐cell lymphomas, such as DLBCL, while cryptic MYC rearrangements—negative by conventional FISH analysis—have been reported in BL." (PMID 35845210, 2021). "In addition, λ-MYC transgenic mice—another model for studying the development of mature B-cell lymphomas —were treated with a combination of NAM and romidepsin with synergistic results in survival." (PMID 35008680, 2021). "Thus, in a λ-MYC transgenic mouse model of endogenously arising B-cell lymphoma, ICB-induced long-term tumor suppression was not only due to the activation of T cells, but also to natural killer (NK) cells." (PMID 33141285, 2021). "Our cohort included samples from chronic lymphocytic leukemia (CLL), follicular lymphoma (FL), diffuse large B-cell lymphoma (DLBCL), high-grade B cell lymphoma with translocations in MYC and BCL2 (HGBL-DH), mantle cell lymphoma (MCL) and marginal zone lymphoma (MZL)." (PMID 33670870, 2021). "In the 1980s, MYC was identified as the first proto-oncogene in B-cell lymphomas." (PMID 33912162, 2021). "Notably, it was demonstrated that MYC inhibited the autophagic pathway in human MYC driven B-cell lymphoma through suppressing the transcription of genes responsible for autophagy." (PMID 34944772, 2021). "Thus, the inhibition of SUMOylation should be explored as a therapeutic option for treatment of MYC-dependent B-cell lymphomas and NPM-ALK+ T-cell lymphomas." (PMID 34503213, 2021). "As the first oncogenic translocation identified in B-cell lymphomas, several transgenic mouse models have been generated over the years to drive MYC overexpression throughout B-cell development under the control of different IG enhancers, in an attempt to mimic the IGH-MYC translocation." (PMID 34456919, 2021).